TRPC5 (transient receptor potential cation channel subfamily C member 5)
Diseases named in the same sentence as TRPC5 in open-access papers (continued):
Sharing a sentence is not in itself a finding about the gene and the disease.
breast carcinoma (continued). "There is evidence that the TRPC5 channel activity increases angiogenesis in cases of breast cancer by the activation of the transcription factor hypoxia-inducible factor 1 (HIF-1), leading to vascular endothelial growth factor (VEGF) formation, thereby promoting cancer growth." (PMID 30463370, 2018). "Therefore, TRPC5 potentiates sensitivity to ADM via the regulation of autophagy in breast cancer cells." (PMID 28600513, 2017). "Blockade of TRPC5 and autophagy augmented breast cancer cell death in response to chemotherapy." (PMID 28600513, 2017). "Moreover, silencing of TRPC5 expression enhanced death and suppressed recovery in breast cancer cells under chemotherapy." (PMID 28600513, 2017). "To determine whether chemotherapy enhances TRPC5 expression and autophagy in breast carcinoma cells, we detected microtubule-associated protein 1 light chain 3 (LC3-I and LC3-II) and TRPC5 by western blotting." (PMID 28600513, 2017). "Thus, our results revealed a novel role of TRPC5 as an inducer of autophagy, and this suggests a novel mechanism of drug resistance in chemotherapy for breast cancer." (PMID 28600513, 2017). "Therefore, we demonstrated that TRPC5 is a negative regulator of drug-induced cell death in breast cancer cells." (PMID 28600513, 2017). "To further investigate the role of TRPC5-induced autophagy in breast cancer cells during chemotherapy, we transfected MCF-7 and MDA-MB 231 cells with full-length human TRPC5 and found that overexpression of TRPC5 significantly increased LC3-II levels and LC3 puncta formation." (PMID 28600513, 2017). "It was suggested that the TRPC5 channel may be involved in breast cancer migration and metastasis." (PMID 37755210, 2023). "In addition, in breast cancer cells, TRPC5 activation promotes autophagy and chemoresistance via the Ca2+/calmodulin-dependent protein kinase beta/adenosine monophosphate-activated protein kinase alpha/mechanistic target of rapamycin (CaMKKβ/AMPKα/mTOR) pathway." (PMID 37892239, 2023). "EA activates TRPC5 channels but it has been suggested that this channel might only rarely be relevant to cancer cell cytotoxicity, although the topic is worthy of further investigation because of the suggested importance of TRPC5 in chemotherapy-resistant breast cancer." (PMID 30038709, 2018). "Therefore, we set out to test this hypothesis by investigating the relationship between TRPC5 and autophagy in drug sensitive/resistance breast cancer cells." (PMID 28600513, 2017). "In adriamycin-resistant breast cancer cells MCF-7/ADM, adriamycin treatment increased TRPC5 expression, leading to the activation of the calmodulin-dependent signaling pathway (CaMKII/AMPKA/mTOR) and chemotherapy resistance." (PMID 38505262, 2024). "Within this review, we will assess the existing understanding of how five specific TRP channels (TRPA1, TRPC5, TRPV1, TRPV2, and TRPM2) contribute to the resistance of breast cancer to therapeutic interventions." (PMID 37755210, 2023). "Thus, TRPC5 may be an important clinical target for the treatment of breast cancer." (PMID 36158191, 2022). "Earlier evidence demonstrated that TRPC5 was up-regulated and induced P-gp overexpression by hyper-stimulating the Ca2+-dependent transcription factor, NFATc3 in chemoresistant MCF-7 breast cancer cells." (PMID 29324706, 2018). "Therefore, TRPC5 may be a good molecular target for the diagnosis and treatment of breast cancer." (PMID 28600513, 2017). "Knockdown of TRPC5 markedly decreased the amount of TRPC5 and the LC3-II level in breast carcinoma cells exposed to ADM." (PMID 28600513, 2017). "Overexpression of TRPC5 significantly increased LC3-II levels and LC3 puncta formation and facilitated futher resistance of breast cancer cells to ADM." (PMID 28600513, 2017). "The Ca2+ channel TRPC5 has been shown to induce resistance in non-resistant breast cancer cells by increasing Ca2+ influx." (PMID 38510751, 2024).
breast carcinoma (continued). "This typically occurs after the transfer of TRPC5, present in extracellular vesicles of resistant breast cancer cells, to non-resistant breast cancer cells." (PMID 38510751, 2024). "It is possible that the observed reduction in receptor-operated Ca2+ signaling, an indirect measure of TRPC5 activity in breast cancer cells, represents a negative feedback mechanism geared towards reducing chronic Gd3+-dependent stimulation of TRPC5 activity." (PMID 37174704, 2023). "However, treatment with Gd-DTPA or GDD significantly increased TRPC5 expression and decreased the accumulation of ADM in the nuclei of MCF-7 and SK-BR-3 cells, promoting the survival of these two breast cancer cells in the presence of ADM." (PMID 37174704, 2023). "Uniquely, TRPC5 on EVs can be intercellularly transferred to non-chemoresistant breast cancer cells, conferring chemoresistance to them due to the increased activity of TRPC5." (PMID 37174704, 2023). "Similarly, TRPC5 expression was induced following doxorubicin treatment in MCF-7, T47D, and MDA-MB-231 breast cancer cells, and its inhibition restored the cytotoxic effects of doxorubicin." (PMID 32575381, 2020). "Unlike TRPC1 and TRPC6, TRPC5 has been identified to mediate chemotherapeutic resistance in breast cancers." (PMID 32211326, 2020). "The endothelial effects of TRPC5 in breast cancer are seemingly limited to T-ECs, as BC-ECFCs do not express this channel." (PMID 29324706, 2018). "This scenario is supported by the observations that HDMECs exposed to TRPC5-contanining EVs, which were collected from adriamycin MCF-7 breast cancer cells, over-expressed the TRPC3-NFATc3-P-gp signaling pathway and developed resistance to adriamycin-induced apoptosis." (PMID 29324706, 2018). "Additionally, it has been suggested that microRNA-320a (miR-320a), which acts as a tumor suppressor, could target and degrade TRPC5 and NFATC3 mRNAs, which are involved in breast cancer chemoresistance." (PMID 37755210, 2023). "Additionally, we found that long-time treatment (4 weeks) of MCF-7, SK-BR-3, and MCF-7/ADM cells with Gd-DTPA and gadodiamide upregulated TRPC5 expression and decreased the accumulation of ADM in breast cancer cell nuclei, which was abolished by TRPC5 antagonist, AC1903." (PMID 37174704, 2023). "To determine whether TRPC5 regulates autophagy in response to ADM, we assessed the LC3-II level and LC3 puncta formation in breast cancer cells transfected with or without TRPC5 siRNA." (PMID 28600513, 2017).
Anxiety (17 papers, 2010 to 2026). Intense feelings of nervousness, tension, or panic often arise in response to interpersonal stresses. "We propose that disruption of TRPC5 in humans causes food-seeking and hoarding behavior, obesity, anxiety, and autism in males and postpartum depression in females." (PMID 38959890, 2024). "Cumulatively, these experiments show that a human LoF mutation in TRPC5 causes obesity, anxiety, reduced sociability, and increased aggressive behavior when modeled in male mice." (PMID 38959890, 2024). "Our results provide strong evidence that acute inhibition of TRPC4 and TRPC5 with HC-070 reduces behavior associated with anxiety and depression in mouse models." (PMID 29385160, 2018). "Studies in murine models have linked TRPC5 activation to fear-related behaviors and anxiety." (PMID 41584354, 2026). "We observed persistent anxiety in TRPC5-deficient people as well as in knockin mice." (PMID 38959890, 2024). "TRPC5, a brain-enriched channel regulating depression and anxiety, is a promising therapeutic target, but current preclinical candidates suffer from moderate off-target effects." (PMID 41584354, 2026). "TRPC5 is highly homologous to TRPC4, and both are involved in the neurobiological mechanisms underlying the regulation of anxiety and depression." (PMID 41584354, 2026). "Annotations between anxiety and the gene AGER, suggest that 129S1/SvImJ mutant of the Trpc5 gene in mice (allele Trpc5tm1.1Clph/Y, by Knockout), decreases anxiety in mouse." (PMID 40560842, 2025). "TRPC5 is frequently discussed as a potential therapeutic target for treating kidney diseases, anxiety, and depression." (PMID 41118703, 2025). "In summary, we demonstrate that genetic disruption of TRPC5 in mice and humans leads to heightened arousal (wakefulness and anxiety), intense food seeking and food hoarding, and impacts on maternal behavior." (PMID 38959890, 2024). "In virgin male and female mice, deletion of Trpc5 from OXT neurons resulted in increased anxiety-like behavior." (PMID 38959890, 2024). "Male TRPC5 deletion carriers exhibited food seeking, obesity, anxiety, and autism, which were recapitulated in knockin male mice harboring a human loss-of-function TRPC5 mutation." (PMID 38959890, 2024). "Hemizygous males and heterozygous females with TRPC5 deletions had a history of anxiety with panic attacks." (PMID 38959890, 2024). "Cumulatively, these studies establish that TRPC5 acts on distinct neuronal populations in the hypothalamus to regulate innate behaviors including feeding, anxiety (flight/fight/fear), socialization, and maternal care." (PMID 38959890, 2024). "There is earlier evidence that the amygdala, highly expressing TRPC4 and TRPC5, is essential in fear, anxiety, and depression." (PMID 36834762, 2023). "Continuing the mechanisms of anxiety, TRPC4 and TRPC5 are heavily implicated in the transmission of conditioned fear responses to the amygdala, and gene disruption in mice demonstrated anxiolytic effects." (PMID 36902145, 2023). "Transient receptor potential canonical 5 (TRPC5) is an ion channel permeable to Na+ and Ca2+ and involved in various conditions, including anxiety, kidney disease, and cardiovascular and metabolic disease." (PMID 34324879, 2022). "TRPC5 plays pathophysiological roles in other diseases, for example pain and anxiety, diabetic nephropathy, cardiovascular disease, rheumatoid arthritis, and cancer." (PMID 30062674, 2019). "Our findings are in good agreement with the recent studies, which reported that gene ablation of either TRPC4 or TRPC5 decreased anxiety-like behaviors in mice." (PMID 26317356, 2015). "Both TRPC4 and TRPC5 have been shown to be involved in anxiety-like behavior in the mouse model of fear conditioning test." (PMID 26317356, 2015). "Subsequently, additional missense variants in TRPC5, resulting in either constitutively open or nonfunctional channels, were linked to cases of intellectual disabilities, anxiety, and autism." (PMID 41118703, 2025).
Anxiety (continued). "In addition, overexpression of Trpc5 in PVH OXT neurons also improved anxiety-like and social behaviors in male Trpc5K34del/Y mutant mice." (PMID 38959890, 2024). "Taken together, these data suggest that TRPC4 and TRPC5 channels may be important targets for the treatment of anxiety and depression." (PMID 29385160, 2018). "In the behaving mouse, inhibition of TRPC4 and TRPC5 results in anxiolytic disinhibition of exploration in a CCK-anxiety model, decreased marble burying, increased activity in tests of antidepressant efficacy, and amelioration of hyper-fear memory in socially stressed mice." (PMID 29385160, 2018). "Genetic deletion of either TRPC4 or TRPC5 reduces anxiety behaviors in mice." (PMID 29385160, 2018). "We speculate that the pro-anxiety role of TRPC5 is relevant to this context and suggest the hypothesis that the unusual metal ion sensitivity of TRPC5 has evolved as an early detection system for metal ion poisoning." (PMID 20100462, 2010). "JDIC-127 significantly ameliorated anxiety-like behaviors in these models across multiple assays, including EPM, OFT, and MBT, supporting a TRPC5-dependent mechanism of action." (PMID 41584354, 2026). "In summary, deletion of Trpc5 from OXT neurons recapitulates the behavioral deficits seen in the humanized Trpc5K34del mice, including anxiety-like behavior, reduced sociability, impaired maternal behavior, and postpartum depression-like behavior." (PMID 38959890, 2024). "Because there are features of anxiety in this model, we probed the effect of inhibiting TRPC4 and TRPC5." (PMID 29385160, 2018). "We provide preclinical evidence that the lack of TRPC4 and TRPC5 channels or its pharmacological inhibition attenuate fear and anxiety without impairing other behaviors in mice." (PMID 39343822, 2024). "TRPC5 is stimulated by receptor agonists and other factors that include lipids and metal ions; it heteromultimerises with other TRPC proteins and is involved in cell movement and anxiety control." (PMID 21291387, 2011).
colon cancer (10 papers, 2019 to 2025). "TRPC5 has been associated with colon cancer progression, and TRPC5 expression is higher in colon cancer samples than in paired normal tissue and also higher in metastatic lymph nodes than in paired primary tumors." (PMID 31275168, 2019). "This article “Overexpression of TrpC5 promotes tumor metastasis via the HIF-1α–Twist signaling pathway in colon cancer” DOI: 10.1042/CS20171069 is being retracted from Clinical Science at the request of the authors and the Editorial Board." (PMID 40457657, 2025). "Colon cancer patients with a high expression of TRPC5 display poorer overall and metastasis-free survival." (PMID 37892239, 2023). "Colon cancer cells with TRPC5 overexpression exhibit increased intracellular Ca2+, which promotes increased migration, invasion and proliferation." (PMID 36158191, 2022). "In colon cancer, overexpressed TRPC5 leads to massive Ca2+ influx, which reduces the expression of E-cadherin." (PMID 36187789, 2022). "TRPC5 also regulates the chemoresistance of colon cancer cells by enhancing Wnt/β-catenin signaling, which increases the expression of P-glycoprotein, an ABC drug efflux transporter, and glucose transporter 1 (GLUT1)." (PMID 36158191, 2022). "Overexpression of TRPC5 in colon cancer cells promotes cancer cell migration and proliferation by inducing epithelial-mesenchymal transition (EMT)." (PMID 36187789, 2022). "TRPC5 promotes the initiation, progression and metastasis of colon cancer by inducing EMT via HIF1ɑ and Twist1." (PMID 36158191, 2022). "Our previous study revealed that poorly differentiated CRC tissues expressed higher levels of TRPC5 in surgically removed colon cancer tissues." (PMID 34422911, 2021). "TRPC5—In colon cancer, TRPC5 was correlated with tumor metastasis, likely by mediating HIF-1α expression and thereby activating Twist and the induction of EMT." (PMID 34360952, 2021). "TRPC5 silencing in highly migratory and invasive colon cancer cells inhibits the migration and invasion, whereas exogenous expression of TRPC5 in colon cancer cells with a weak migration and invasion ability promotes an increase in these parameters." (PMID 31275168, 2019). "The TRPC5 channel seems to promote metastasis in colon cancer." (PMID 37892239, 2023). "In addition to chemoresistance, TRPC5 expression was observed to be positively correlated with high proliferative, migratory, and invasive abilities of colon cancer cells, promoting the EMT through the HIF-1α-Twist signalling pathway." (PMID 35806388, 2022). "The same research group also validated TRPC5 role in mediating HIF-1α response in tumour progression in colon cancer, where TRPC5 activated the HIF-1α-Twist signalling pathway to promote EMT, migration and proliferation in SW620 colon cancer cells." (PMID 35806388, 2022). "Therefore, overexpression of TRPC5 promotes the migration and proliferation of colon cancer cells through the TRPC5/HIF-1α/Twist signaling pathway, and TRPC5 and HIF-1α may become potential therapeutic targets for colon cancer." (PMID 36187789, 2022).
colorectal cancer (10 papers, 2016 to 2025). A primary or metastatic malignant neoplasm that affects the colon or rectum. "Further studies in patients with advanced colorectal cancer implementing chemo-therapy showed that the effect of high TRPC5 expression on chemo-resistance was dependent on high GLUT1 expression." (PMID 36033489, 2022). "The up-regulated expression of TRPC5 was shown to activate glycolysis in human colorectal cancer cells via the Wnt/β-catenin signaling pathway which has been shown to induce GLUT1 expression through c-Myc." (PMID 36033489, 2022). "The same team demonstrated the essential role of glycolysis in TRPC5 induced chemoresistance in human colorectal cancer cells by maintaining Ca2+ homeostasis." (PMID 30884858, 2019). "In colorectal cancer, TRPC5 overexpression induces the Wnt/β-catenin signalling pathway and the up-regulation of MDR1." (PMID 30884858, 2019). "TRPC5 suppression also appears to be essential to drug resistance in colorectal cancer, where suppression of TRPC5 expression reduced MDR1 induction, leading to 5-FU resistance via the canonical Wnt/β-catenin signal pathway." (PMID 29636894, 2018). "Notably, MKN-45 and DLD-1 exhibited the highest TRPC5 protein expression among the respective gastric and colorectal cancer cell lines, leading to their selection for subsequent in vitro and in vivo studies." (PMID 39309444, 2024). "On the contrary, TRPC5 has increased in 5-FU-resistant colorectal cancer cells HCT-8/5-FU and LoVo/5-FU cell lines, therefore blockade of TRPC5 promotes chemosensitivity in these cells." (PMID 32575381, 2020). "In our previously study, up-regulated expression of transient receptor potential canonical channel (TRPC5) was proven to increase [Ca2+]i level, and resulted in chemoresistance whereas not apoptosis in human colorectal cancer (CRC) cells." (PMID 29463225, 2018). "Additionally, compared to normal gastric epithelial cells (GES-1) and colon epithelial cells (NCM460), TRPC5 mRNA and protein levels were markedly elevated in gastric cancer cell lines (MGC-803, BGC-823, MKN-45, AGS) and colorectal cancer cell lines (HCT-116, DLD-1, SW480, SW620)." (PMID 39309444, 2024).